IL1B (interleukin 1 beta)
Diseases named in the same sentence as IL1B in open-access papers (continued):
Sharing a sentence is not in itself a finding about the gene and the disease.
colitis (continued). "It has been demonstrated that TNFα, as well as other cytokines (IL-1β and IL-6) are elevated in colon tissue in response to DSS-induced colitis by our group and countless others." (PMID 25460165, 2014). "We previously observed that cytokines such as IL-1β, IL-6 and MIP-2 were up-regulated in an animal model of colitis." (PMID 24520376, 2014). "We have investigated the production of cytokines including IFN-γ, IL-1β, IL-6, IL-10, IL-12 (P40), IL-12 (P70), IL-17, and TNF-α in colonic mucosa of mice with experimental colitis." (PMID 24948848, 2014). "COX-2 has been involved in LPS- and IL1β-induced anorexia, Asarian and Langhans (2010), which is also a symptom of IBD, of TNBS acid-induced colitis in rats and of DSS-induced colitis in mice." (PMID 25414650, 2014). "Pro-inflammatory cytokines such as TNF-α, IL-1β, and IL-6 were detectable in both SIGNR3−/− and wild-type mice upon induction of DSS colitis." (PMID 23882266, 2013). "Such a decrease in IL-1β was previously reported by Hirano and Kudo after treatment of CD45RB transfer colitis mouse model with both dexamethasone and anti-tumor necrosis factor-α (anti-TNF-α)." (PMID 23198878, 2012). "MIF was significantly over-expressed only 24 h after TNBS administration (p<0.05) while colonic levels of IL-1β were markedly increased at 24 h, 3 d and 5 d after TNBS-induced colitis (p<0.01)." (PMID 23166707, 2012). "A significant increase of mRNA and protein expression of IL-1β and TNF-α, as assessed by real-time quantitative RT-PCR and ELISA, respectively, was observed in saline-treated mice with DSS-induced colitis compared with the normal control group (P < 0.05)." (PMID 23125487, 2012). "In fact, proinflammatory cytokines of the Th1-type of immune response such as TNF-α and IL-1β are known to be present in high levels in CD and in TNBS-colitis." (PMID 22432015, 2012). "Meanwhile oral administration of picroliv significantly reduced IL-1β, TNF-a mRNA expression increased in the clonic tissues of DSS-induced colitis by inhibiting the expression of NF-κB p65." (PMID 23125487, 2012). "Proinflammatory cytokines (e.g., TNF-α, IL-1β, and IL-6) liberated from macrophages, neutrophils, and endothelial cells were shown to be overproduced in TNBS-induced colitis and in human IBD." (PMID 22888336, 2012). "Pro-inflammatory cytokines like macrophage migration inhibitory factor (MIF), IL-1β and TNF-α predominate in inflammatory bowel diseases (IBD) and TNBS colitis." (PMID 23166707, 2012). "In the present study, we observed an elevation of the proinflammatory cytokines, such as TNF-α and IL-1β, in DSS colitis tissue." (PMID 23125487, 2012). "The increase in the amount of IL-1β and TNF-α mRNA and protein in the mice with DSS-induced colitis was reduced significantly following the treatment with picroliv." (PMID 23125487, 2012). "The proinflammatory cytokines IL-1β and IL-6 have been reported to be upregulated in the acute DSS colitis model." (PMID 21858054, 2011). "Rb1 and compound K appear to block IRAK-1 and NFκB activation and thereby reduce pro-inflammatory cytokines, IL-1β, TNF-α and IL-6 and cytokine effectors iNOS and Cox-2 in 2,4,6-trinitrobenzene sulfonic acid (TNBS)-treated mice, another model of colitis." (PMID 22070864, 2011). "Intrarectal administration of poly P also suppressed the production of inflammatory cytokines IL-1β and IL-6 in mice colons with DSS-induced colitis." (PMID 21858054, 2011). "Marked induction of IL1β, IL6, TGFβ and IL23A, genes involved in the differentiation of Th17 cells, was observed in colonic inflammation." (PMID 21144017, 2010). "In chronic DSS-induced colitis, both decreased expression of pro-inflammatory cytokines (TNF-α, NO, and IL-1β) and increased anti-inflammatory mediators (IL-10) in the colonic mucosa contributed to attenuate inflammation after Resveratrol treatment." (PMID 21151942, 2010).
colitis (continued). "DSS colitis in the VDR KO mice was accompanied by high colonic expression of TNF-α, IL-1 α, IL-1β, IL-12, IFN-γ, IL-10, MIP-1α and KC." (PMID 17397543, 2007). "Examining the expression of cytokines, we found significantly elevatedmRNA levels of proinflammatory cytokines IL-1β, IL-6, GM-CSF, and TNFα in micewith TNBS-induced colitis." (PMID 18288268, 2007). "Samples were collected 7 days after colitis induction, for intestinal bacterial flora, bacterial translocation, short chain fatty acids (SCFAs), myeloperoxidase (MPO), cytokines (IL-1β, TNF-α, IL-10 and TGF-β) and malondialdehyde (MDA)." (PMID 17069659, 2006). "In addition, the results implied that the mice in TNBS + MSC + SIS group had alleviated colitis compared with the TNBS + MSCs group, and the interleukin (IL)-1β and tumor necrosis factor-α (TNF-α) levels in the serum also decreased." (PMID 42218603, 2026). "Similarly, the concentrations of inflammatory factors in the blood of colitis mice in the A. actinomycetemcomitans gavage group were also significantly higher than those in the DSS group (IL-6, P = 0.002; IL-1β, P = 0.002; TNF-α, P = 0.004)." (PMID 41531455, 2026). "In conclusion, DBK successfully reduced inflammation in DSS-induced UC mice by modulating the IL-6/IL-6R and IL-17A/IL-17RA pathways, as evidenced by alleviated colitis symptoms, decreased pro-inflammatory cytokines (TNF-α, IL-6, IL-1β), and histological improvements." (PMID 40005956, 2025). "Moreover, ELISA analyses demonstrated that quercetin alleviated colonic inflammation by significantly decreased the levels of IL-1β, IL-6, and TNF-α by 23.2 %, 19.9 %, and 20.7 %, respectively, in colitis mice." (PMID 40909112, 2025). "The DSS group showed a significant increase in the gene expression levels of TNF-α, IL-1β, and IL-6 in the colon (p < 0.001), which was consistent with the serum findings, indicating a strong correlation between DSS-induced colitis and heightened cytokine expression in the colon." (PMID 40238198, 2025). "In mice with DSS-induced colitis, levels of the pro-inflammatory cytokines TNF-α, IL-1β, and IL-6 were significantly elevated, whilst the anti-inflammatory cytokine IL-10 was markedly decreased, indicating an intense inflammatory response and immune dysregulation." (PMID 40777179, 2025). "It was shown that increased O-linked N-acetylglucosamine modification (O-GlcNAcylation) of STAT3 upregulated the expression of proinflammatory cytokines such as IL-6, IL-1β, and TNF-α, while downregulating the level of the anti-inflammatory cytokine IL-10 and aggravating colitis in mice." (PMID 40078988, 2025). "Wedelolactone markedly reduced the IL-1β-induced expression of COX-2, iNOS, TNF-α, and IL-6 in human chondrocytes by inhibiting NF-κB activation and further attenuated colonic inflammation in DSS-induced colitis via suppression of the IL-6/STAT3 axis." (PMID 41304898, 2025). "In addition, I3C therapy significantly reduced the mRNA expression of proinflammatory cytokines IL‐1β, IFNγ, and TNFα in DSS‐induced colitis mice." (PMID 40410944, 2025). "Therefore, high succinylation of PKM2 reduces its pyruvate kinase activity yet increases its protein kinase activity, thereby regulating the secretion of inflammatory factor IL-1b and playing a role in DSS-induced colitis in mice." (PMID 40865948, 2025). "These anti-inflammatory and antioxidant effects have been similarly reported in various pathological models, including colitis, ischemia–reperfusion injury, and diabetes, where MB administration reduced TNF-α, IL-1β, IL-6, and CRP levels, suppressed MPO and MDA, and enhanced SOD activity." (PMID 40870501, 2025). "Moreover, dietary resveratrol attenuated the inflammatory status and down-regulated the expression of proinflammatory cytokines such as IL-2, IFN-γ, IL-1β, IL-6, and TNF-α in colitis mouse model." (PMID 40078988, 2025).
colitis (continued). "By suppressing this pathway, MP may reduce the production of pro-inflammatory cytokines, such as IL-1β, TNF-α, and IL-6, thereby alleviating colitis symptoms." (PMID 40012624, 2025). "Interestingly, PPT with an anti-inflammatory effect (e.g., suppression of IL-6, IL-1β, and TNF-α) ameliorated colitis, resulting in the recovery of body weight and colon length." (PMID 40141242, 2025). "Similarly, QA has been shown to lower IL-1β, iNOS, IL-6, and TNF-α expression in a mouse colitis model." (PMID 40538727, 2025). "CW supplementation inhibits the high levels of inflammation induced by DSS, suppressing excessive inflammatory mediators (serum TNF‐α, IL‐1β, and IL‐6), downregulating the overexpressed mRNA levels of TNF‐α, IL‐1β, IL‐6, TLR4, and iNOS, while upregulating IL‐10, thereby alleviating colitis." (PMID 39830908, 2025). "In 2,4-dinitrobenzene sulfonic acid (DNBS)-induced colitis, treatment with verbascoside improved macroscopic damage, body weight, and inflammatory markers (TNF-α, IL-1β) while reducing oxidative stress and metalloproteinase activity (MMP-2 and MMP-9) in colon tissue." (PMID 40724000, 2025). "Moreover, levels of pro-inflammatory cytokines including IL-6, IL-1β, and TNF-α were notably reduced, whereas anti-inflammatory cytokine IL-10 was notably increased after YTA treatment in colitis mice." (PMID 41476793, 2025). "While IL-1β response amplitudes were not significantly decreased in DSS-colitis, there were decreases in other IL-1β neural response features." (PMID 40268933, 2025). "Therapy with nicotine reduced TNF production in the colon and improved colitis, but subdiaphragmatic vagotomy of the ventral and dorsal vagus nerves raised the colitis disease activity score and markedly elevated TNF, IL-6, and IL-1b production in colon tissue." (PMID 39828740, 2025). "Mice transplanted with the colitis microbiome showed higher expression of IL-6, IL-1β, and TNF-α in the colon than mice transplanted with the normal mouse microbiome." (PMID 40076732, 2025). "Furthermore, compared with the control group, RT-PCR revealed that there was an obvious increase in the expression of the typical inflammation-related cytokines, mainly including TNF-α, IL-6, IL-1β, and iNOS in the DSS-induced colitis model." (PMID 40255504, 2025). "Indeed, increased concentrations of IL-1β, TNF-α, and IFN-γ in DSS colitis was accompanied by the expansion of functional MDSCs." (PMID 40244120, 2025). "Furthermore, SPDD weakened the interaction between MAPK4 and AKT, resulting in a decrease in the phosphorylation level of AKT, thereby reducing the expression of IL-6, IL-1β, iNOS, and COX-2, and alleviating colitis (p < 0.05)." (PMID 40238233, 2025). "Similarly, in DSS-induced colitis, MHV-68 infection resulted in significant expression of GSDMD, NLRP3, IL-1β, and IL-18 in peritoneal macrophages." (PMID 40041420, 2025). "In this study, the levels of IL-1β, IL-6, and TNF-α in enteritis model mice were significantly higher than those in the control group, indicating that systemic inflammation was triggered when DSS-induced colitis." (PMID 40238292, 2025). "IL-1β and IL-6 serum levels were significantly higher in the model and CDP groups, while CEA and AFP levels exhibited similar trends, indicating that CDPs facilitate the development of internal tumors in colitis mice models." (PMID 40911847, 2025). "In a DSS-induced experimental colitis model in rats, PNS demonstrated the ability to suppress the PI3K/Akt signaling pathway, reduce oxidative stress, and lower pro-inflammatory cytokines such as IL-6, IL-1β, and TNF-α." (PMID 40417220, 2025). "At the same time, the results of SAKAI showed that AST could inhibit the expression of inflammatory factors (IL-1β, IL-6, TNF-α, and COX-2) in mice and ultimately alleviate the development of colitis." (PMID 40867814, 2025).
colitis (continued). "So, FL-BsAb1/17 antibody targeting IL-1β and IL-17A inhibited the development of DSS-induced UC and may have potential as a candidate for colitis treatment." (PMID 38491049, 2024). "Similarly, previous research has also found that PA can effectively inhibit the elevation of IL-1β, IL-6, and TNF-α levels in colitis." (PMID 39064674, 2024). "Further, in an acetic acid-induced colitis model and caco-2 colon epithelial cells, cyclooxygenase-2 (COX-2) inhibitor (mangiferin) prevents activation of NLRP3 and expression of inflammatory markers such as IL-1β, TNF-α, IL-16, and IFN-γ." (PMID 39769450, 2024). "Similarly, in DSS-induced colitis mice, S. cerevisiae strain QHNLD8L1 contributed in IL-1β reduction and IL-10 increase, with further inflammation response regulation." (PMID 39628717, 2024). "Secondly, B. bifidum has immune-regulatory functions, inhibiting the expression of inflammatory factors interleukin (IL)-1β, tumor necrosis factor (TNF)-α, IL-6, and interferon (IFN)-γ, while promoting IL-10 expression, thus facilitating gut damage repair in colitis mice." (PMID 39525506, 2024). "Also, sinapic acid reduces serum levels of proinflammatory cytokines (TNF-α, IL-1β, IL-6, IL-17α, IL-18, and interferon (IFN)-γ) and increases anti-inflammatory cytokines (IL-4 and IL-10) in Kunming mice with DSS-induced colitis." (PMID 38732594, 2024). "Suppress colitis-stimulated tissue oxidative stress.Suppress TNF-α, IL-6, IL-1β, and IL-33." (PMID 38585461, 2024). "Cytokines are important mediators of inflammation and elevated levels of major proinflammatory cytokines such as tumor necrosis factor (TNF), interleukin (IL)-6, IL-1β, and interferon-gamma (IFN-γ) are observed in patients with ulcerative colitis and also in chemically induced colitis models." (PMID 38998493, 2024). "Mice with DSS-induced colitis exhibited significantly elevated levels of IL-6, TNF-α, and IL-1β." (PMID 39296302, 2024). "We observed the attenuation of the severity of colitis in mice treated with MC-170073, as indicated by the downregulation of macroscopic and histological scores along with lower levels of MPO and the proinflammatory cytokine IL-1β." (PMID 38713616, 2024). "Also, these compounds possess anti-inflammatory properties, suppressing inflammatory pathways involved in colitis and inhibiting the NLRP3 inflammasome, thereby reducing pro-inflammatory cytokines like IL-1β, IL-6, and TNF-α." (PMID 39061864, 2024). "In addition, the graph illustrates the significant reductions in the IL‐1β, IL‐6, and TNF‐α expression levels following BLF administration, further supporting the anti‐inflammatory effect of BLF in AD mice with colitis." (PMID 38334213, 2024). "During colitis relapse, it improved histological inflammation and biochemically inhibited MPO, alkaline phosphatase, and metalloproteinase 9 activities, while also decreasing MDA and IL-1β levels." (PMID 39494333, 2024). "Interestingly, when we treated the infected colitis mice with LGG or BL, we observed a significant increase in IL-6, CXCL2, IL-1β, TNF-α, IL-17a, and IL-22 gene expression in the cecal tissue, indicating an enhanced inflammatory response." (PMID 38397855, 2024). "The lack of both the IL-1β and IL-18 receptors causes a greater susceptibility to DSS-induced colitis and CRC development." (PMID 39684769, 2024). "In addition, the upregulated expression levels of downstream genes in colitis mice after DVF challenge, including Cxcl9, Cxcl10, IL1β, and Tnf-α, were significantly decreased by typhaneoside." (PMID 38172943, 2024). "Additionally, hydroxytyrosol has been shown to lower levels of IL-1β, IL-6, and TNF-α and increase the level of the anti-inflammatory cytokine IL-10 to ameliorate intestinal inflammation in mice colitis models." (PMID 38891778, 2024). "However, lactic acid bacteria enriched in the colitis group showed a strong inverse correlation with colonic TNF-α, IL-1β,and IL-6 levels (p < 0.05)." (PMID 38528541, 2024).
colitis (continued). "Studies conducted on mice with colitis have demonstrated that intact CPP is more efficacious in reducing the expression of pro-inflammatory factors IL-6, CXC motif chemokine ligand 2 (CXCL2), IL-1β, and TNF-α than a single CPP extract." (PMID 39839098, 2024). "After measuring the levels of pro-inflammatory cytokines in the serum of each group of mice, we found that compared to the control group, the levels of TNF-α (p < 0.001), IL-1β (p < 0.01), and IL-6 (p < 0.05) were significantly increased in the serum of mice with DSS-induced colitis." (PMID 38474831, 2024). "In addition, DEGs associated with the immune receptor (Lrrc19), cell chemotaxis (Ccr7, Cxcl1, Cxcl5, Cxcl9, and Cxcl10), and inflammatory response (IL1r11, IL11, Tnf, IL1β, and IL18) were also upregulated in the colonic tissue of colitis mice in DVF group." (PMID 38172943, 2024). "The results revealed significant IL‐1β, IL‐6, and TNF‐α pro‐inflammatory cytokine up‐regulation in the UC model group (p < 0.05), suggesting the presence of an inflammatory response in the mice with colitis." (PMID 38334213, 2024). "In a study on DSS-induced colitis in mice, CSCC exhibited powerful anti-inflammatory effects by inhibiting the JNK1/STAT3 signaling pathway, reducing the levels of pro-inflammatory cytokines TNF-α, IL-1β, and IL-17." (PMID 39329121, 2024). "Additionally, at doses of 20 and 40 mg/kg, ferulic acid ameliorated TNBS-induced colitis by inhibiting the production of proinflammatory cytokines (TNF-α, IL-1β, IL-6, AND IL-10) and downregulating COX-2 synthesis." (PMID 38732594, 2024). "Many studies have shown that cytokines IL-6, IL-1β, and TNF-α play an important role in colitis." (PMID 38398846, 2024). "Other studies have reported that hyperalgesia owing to central sensitization via TRAF6/nuclear factor-κB (NF-κB) was observed in visceral pain models, as knockdown of TRAF6 suppressed colitis-induced activation of NF-κB and increased TNF-α and IL-1β in the spinal cord." (PMID 39044893, 2024). "Similarly, oral administration of another AhR agonist, β-naphthoflavone, was shown to decrease the severity of DSS-induced colitis while reducing pro-inflammatory cytokines such as tumor necrosis factor -α (TNF-α), IL-6, and IL-1β." (PMID 39767818, 2024). "To gain a deeper understanding of the mechanism by which TP2 alleviates colitis, we utilized ELISA technology to assess typical pro-inflammatory and anti-inflammatory cytokines in rats’ colonic tissues, including TNF-α, IFN-γ, IL-1β, IL-6, IL-10, IL-17A, IL-22, and IL-23." (PMID 39776580, 2024). "Finally, PR1P prevented weight loss and tissue injury and reduced plasma levels of key inflammatory cytokines IL-1β and IL-6 in a TNBS-induced colitis model in the rat." (PMID 37187742, 2023). "In contrast, the IL-1β expression in macrophages was suppressed by the TRPA1 agonist cinnamaldehyde and the TRPA1 agonist cannabinoid reduces INF-γ in macrophages by inhibiting nitric oxide (NO), thus exerting an anti-inflammatory role in colitis in mice." (PMID 37834182, 2023). "Finally, PR1P prevented weight loss and tissue injury and reduced plasma levels of key inflammatory cytokines IL-1β and IL-6 in a rat TNBS-induced colitis model." (PMID 37187742, 2023). "Inhibiting IL-1β production by MCC950 failed to relieve the symptoms of colitis when it was used after colitis induced but significantly ameliorated the colitis with subsequent C.difficile invasion." (PMID 36951545, 2023). "In addition, the levels of oxidative stress (MPO, SOD, and MDA) and inflammatory cytokines (TNF-α, IL-1β, IL-6, and IL-10) were reversed by PHI in colitis mice." (PMID 36768559, 2023). "In our study, L. sakei CVL-001 administration led to decreased gene expression levels of pro-inflammatory cytokines, such as IL-1β, TNF-α, and IL-6, and increased gene expression levels of anti-inflammatory cytokines, such as IL-10, against DSS-induced colitis." (PMID 37317332, 2023).